MTOR (mechanistic target of rapamycin kinase)
Diseases named in the same sentence as MTOR in open-access papers (continued):
Sharing a sentence is not in itself a finding about the gene and the disease.
tumor (continued). "TPT1 was one of the direct targets of miR-216a-5p and contributed to miR-216-5p-induced tumor malignancy via mTOR-dependent autophagy." (PMID 32792860, 2020). "Through Western blotting, it also confirmed that LNT not only reduced the levels of VEGF and HIF-1α in tumor tissues, but also inhibited the activity of Akt and mTOR." (PMID 33245358, 2020). "Although the mTOR kinase was found unaltered both at the transcriptional and protein level, the levels of activated p-mTOR (Ser2448) were found more than 2-fold higher in tumor specimens compared to the normal tissue." (PMID 33092114, 2020). "Although targeting the mTOR signaling pathway exerts potent anti-tumor activity, little is known about specific mTORC2 inhibition regarding liver metastasis." (PMID 33375117, 2020). "Constitutive activation of mTOR restored the proliferation rate in the PDAC cells with PDP1 knockdown, suggesting that mTOR activation is essential for PDP1-driven tumor cell growth in PDAC." (PMID 32782783, 2020). "It has been demonstrated that AMPK inhibits the mammalian target of rapamycin (mTOR), partially explaining its anti-tumor effects." (PMID 32647571, 2020). "NF-κB is constitutively over-expressed in GBM, and its aberrant activation is linked to de-regulated, tumor-promoting EGFR and PI3K/Akt/mTOR signaling." (PMID 33092261, 2020). "Some studies have shown that ENO1 acts as a potent promoter in tumor cells by regulating AMPK/mTOR and PI3K/AKT signaling and inactivating a downstream signaling pathway." (PMID 33226369, 2020). "In this tumor type, PD-L1 expression is increased by PI3K/Akt/mTOR activation mediated by either Phosphatase and tensin homolog (PTEN) inactivation or loss, or mTOR activation." (PMID 33114576, 2020). "We observed that the mTOR and p-mTOR expression were higher in Black women than White women after adjusting for tumor characteristics and BMI." (PMID 33024820, 2020). "Another study reported that mefloquine prevents the proliferation of the gastric cancer cells and reduced tumor growth in xenograft mouse models by inhibition of PI3K/Akt/mTOR pathway." (PMID 33028364, 2020). "A key criterion was the achievement of complete inhibition of mTOR dependent-signaling pathways on tumor and skin biopsies." (PMID 33304317, 2020). "The interplay between MTEX and myeloid stem cells (MSCs) induce the emergence of a tumor-like phenotype with PD-1 and mTOR overexpression in naïve MSCs in vitro and fast tumor progression in vivo." (PMID 32709086, 2020). "At the same time, the genomic landscape of PanNETs has been comprehensively characterized, reaffirming molecular alterations in telomere maintenance and the mTOR pathway as indicators of aggressive tumor behavior." (PMID 32850899, 2020). "Transitioning between highly proliferative (mTOR high; unstressed) and relatively dormant (mTOR low; stressed) states is likely requisite for tumor growth and plasticity, respectively." (PMID 32427827, 2020). "As the patient was now completely free of disease, and since no data about a beneficial continuous pharmacological therapy were available, the local tumor board decided to discontinue mTOR inhibitor therapy." (PMID 31309284, 2020). "mTOR signaling pathway plays a central role in metabolic reprogramming of tumor cell growth and proliferation." (PMID 32984331, 2020). "Consistent with our above and previous results, baicalein had more potent suppressive effect on mTOR signaling in tumor cells than that of baicalin." (PMID 32984331, 2020). "DDIT4, a regulator of the mammalian target of rapamycin (mTOR) kinase, has been shown as an important protein in tumor development due to its tumor suppressing properties." (PMID 32717951, 2020).
tumor (continued). "In summary, targeting PLK1 lead to a striking tumour regression in three out of fpur CCND1-driven PDX models, while AKT1 and mTOR mutated PDX preferably responded to AKT1 and mTOR inhibitors." (PMID 32792481, 2020). "Tumor volume reduction over 50% was defined as a significant treatment effect in the present study to compare with that of mTOR inhibitors for AMLs in the EXIST-2 trial." (PMID 33219488, 2020). "Here, we report a novel regulatory link between mTOR complexes (mTORCs) and tissue factor (TF), an initiator of tumor-derived thrombosis." (PMID 32923403, 2020). "We also found induction of PMEL, CD171/L1 and mTOR at progression in tumor biopsies from two matched cases of patients receiving targeted therapy with BRAFi." (PMID 33082316, 2020). "MicroRNA-99a has a tumour suppressive role in the mammalian target of rapamycin (mTOR) signalling pathway." (PMID 33023154, 2020). "Knockdown of S100A10 expression suppresses the activation of the mTOR pathway, thus inhibiting glycolysis and tumor growth." (PMID 33324631, 2020). "Tumor type (p = 0.46), expression of p-mTOR (p = 0.011), expression of EGFR (p = 0.046), and expression of PD-L1 (p = 0.023) had a significant impact on the targeted therapy recommendation rate." (PMID 33114048, 2020). "In this study, the anti-tumor efficiency of mTOR inhibitor RAD001 (Everolimus) was tested in vitro and in vivo with special emphasis on signaling pathways to get more details on the local surviving or selected cells." (PMID 32373532, 2020). "PTEN is a tumor suppressor gene that classically dampens the PI3K/AKT/mTOR growth-promoting signaling cascade." (PMID 33308182, 2020). "In the further study, we found that co-treatment with baicalin and Akt activator SC79 significantly attenuated the decreased tumor size and upregulated the expression of p-Akt, p-mTOR, CDK4, and Cyclin E2, when compared with baicalin treatment alone." (PMID 33585556, 2020). "Taking together, the present work based on the CEA424-SV40 T antigen tumor mouse model system provides supportive evidence for the anti-tumor potential of the mTOR inhibitors." (PMID 32373532, 2020). "Copanlisib exerted the most potent anti-tumor growth effects on MCC cells by suppressing PI3K/mTOR/Akt activities." (PMID 32483262, 2020). "Since mTOR signaling can be regarded as the tumor driver in these cases, its inhibition represents a promising target for pharmacologic therapy." (PMID 31309284, 2020). "miR-27a hampered AMPK, enhanced mTOR signalling and acted in concert with oncogenes and tumour cell metabolic regulators to force an aerobic glycolytic metabolism supporting biomass production, unrestricted growth and chemoresistance." (PMID 32132656, 2020). "Concomitantly, compelling evidence indicates that AMPK activation has emerged as a pivotal negative regulator of mTOR and its downstream effectors, which intimately relates to tumor invasion and metastasis." (PMID 32719745, 2020). "Recent studies also show that PI3K/AKT/mTOR pathway also functions in tumor cell metabolisms such as glycolysis, lipid metabolism and amino acid metabolism." (PMID 32547948, 2020). "Further analysis of the MPNST xenograft tumours resistant to AKT/mTOR treatment revealed a reactivation of both AKT and mTOR in several tumour samples." (PMID 32102484, 2020). "Accordingly, mTOR interacts with the upstream molecule mesenchymal–epithelial transition factor (c-met) to regulate tumor progression." (PMID 32823876, 2020). "Numerous studies have suggested that AKT/mTOR is involved in the Warburg effect by activating HIF-1α or c-Myc in tumor cells." (PMID 32685545, 2020).
tumor (continued). "Loss of FAK and treatment with a FAK inhibitor (PF-562271) suppressed tumor growth and the invasion ability of ES cells in vivo and in vitro by suppressing Crkl-associated substrate (CAS) activity and the AKT/mTOR pathway." (PMID 32754598, 2020). "Phosphatases and tensin homolog (PTEN) is an important tumor suppressor gene that negatively regulates the PI3K/Akt/mTOR anti-apoptotic pathway." (PMID 32823876, 2020). "In terms of mechanism, other studies have suggested that PD‐L1 signal in tumor cells can promote the ability of glycolysis in tumor cells by activating AKT/mTOR pathway." (PMID 32875727, 2020). "One striking finding in our in vivo series was the residual activity of the PI3K/AKT/mTOR signalling pathway in the treated tumours." (PMID 32102484, 2020). "The resected tumor showed large necrotic areas, accounting for about 50%, which were evaluated as effects of mTOR inhibitor therapy." (PMID 31309284, 2020). "This hyperactivation of mTORC1 augmented the phosphorylation and activation of mTOR-Drp1, leading to mitochondrial fragmentation and failure in their anti-tumor effector functions." (PMID 33240877, 2020). "In this study, we proposed a therapeutic strategy of targeting mTOR for remodeling the tumor metabolism and TIME via a BBB-penetrating liposomal system for codelivery of honokiol (HNK) and disulfiram/copper (DSF/Cu) complex." (PMID 32817393, 2020). "Recently, further investigations have been performed to explore how the mTOR signal transduction mechanisms modulate sensitivity of targeted therapies, angiogenesis, and tumor immunity." (PMID 33014055, 2020). "Meanwhile, ncRNAs also participate in the regulation of cell metabolism through the PI3K/AKT/mTOR pathway, thus affecting tumor cell metastasis." (PMID 32547948, 2020). "The central checkpoint for the negative regulation of autophagy is mTOR, and anti-tumor drugs stimulate autophagy by attenuating the PI3K/AKT/mTOR pathway." (PMID 32373608, 2020). "And mTOR is an important serine-threonine protein kinase downstream of the PI3K/Akt signaling pathway which can regulate the malignant biological process of tumor cells by activating ribosomal kinase." (PMID 33282634, 2020). "APOE activated the PI3K/AKT/mTOR signaling pathway and played an important regulatory role in angiogenesis, tumor cell growth, and metastasis." (PMID 33015179, 2020). "Activation of PI3K further promoted phosphorylation of Akt on Ser473 and activation of mTOR, which involved in regulating the growth and migration of tumor cells." (PMID 33375426, 2020). "PTX3 interacts with the PI3K/AKT/mTOR signaling pathway to induce tumor cell proliferation, apoptosis and metastasis in lung cancer, head and neck squamous cell carcinoma and breast cancer." (PMID 33013829, 2020). "We performed staining of the tumor sections through immunohistochemistry (IHC) and/or immunofluorescence (IF) to assess mTOR-targeted inhibition of TF." (PMID 32923403, 2020). "In brief, our study implied that the GAL1 protein is highly associated with oncological outcomes of UTUC by promoting tumor invasion, metastasis, and epithelial–mesenchymal transition, possibly through the FAK/PI3K/AKT/mTOR pathway." (PMID 32225123, 2020). "With DEGs pathway analysis applied in KEGG, we find two important tumor-related pathways, Wnt and mTOR." (PMID 31676945, 2020). "In NSCLC, decreased miR-193a-5p and miR-193a-3p expressions linked to enhanced tumor metastasis through upregulating PIK3R3 and mTOR as well as ERBB4 and S6K2, respectively." (PMID 32316322, 2020). "A brain-targeted liposomal honokiol and disulfiram/copper codelivery system (CDX-LIPO) was developed for combination therapy via regulating mTOR (mammalian target of rapamycin) pathway for remodeling tumor metabolism and TIME." (PMID 32817393, 2020). "Recent studies have shown that a hypoxic condition established by the tumor initiates and sustains the activation of mTOR-GTPase dynamin-related protein-1 (mTOR-Drp1)." (PMID 33240877, 2020).
tumor (continued). "mTOR inhibitor, it reduces the metabolic rate, augments differentiation and inhibits tumor formation." (PMID 34766113, 2020). "Our findings further revealed a significant decrease in the inhibitory signal to T cells co-cultured with PG2-treated tumor cells as seen in the activated protein kinase B (Akt)/mammalian target of rapamycin (mTOR) pathway in immune cells." (PMID 32308547, 2020). "To gain additional evidence for the observed difference in immune cell composition between the tumour groups being driven by mTOR signalling in TAM‐MG, we looked at the signalling activity of TAM‐MG compared to TAM‐BMDM in GBM from group 1." (PMID 32567735, 2020). "Immunoblot assay showed that KDELC2 knockdown promoted tumor apoptosis by downregulating PI3k/mTOR/Akt, MAPK/ERK, and NF-kB pathways." (PMID 32927743, 2020). "Previous studies have also highlighted activation of the mTOR pathway in tumor cells resistant to MET TKIs28,36." (PMID 33082316, 2020). "The activated AKT regulates the cell proliferation, survival, invasion and metastasis of tumor cells by phosphorylating multiple downstream factors such as mTOR, protein kinase and transcription factor." (PMID 33117085, 2020). "The PI3K/AKT/mTOR pathway, as the major downstream pathway for most RTKs, has become the focus of research on the malignant behavior of tumor cells." (PMID 32041519, 2020). "The PI3K/Akt/mTOR signaling cascade is another major signaling pathway implicated in HCC carcinogenesis and plays a central role in driving tumor cell proliferation." (PMID 32155915, 2020). "The relationship among miR-20a-5p, WTX, and PI3K/AKT/mTOR pathway were farther verified in miR-20a-5p-modified subcutaneous GC tumours." (PMID 33032635, 2020). "Vigorous glucose consumption by tumor cells metabolically compete with infiltrating T cells and hyponutrition in T cells reduced mammalian target of rapamycin (mTOR) activity, glycolysis and cytokine production such as interferon (IFN)-γ." (PMID 32913271, 2020). "Downregulation of DGKA and its downstream targets HIF-1α and mTOR resulted in suppression of tumor cell migration and survival." (PMID 32477950, 2020). "This was further observed alongside PTEN loss and overexpression of Akt and mTOR, suggesting activation of the PI3K/Akt/mTOR pathway in these tumours." (PMID 32725435, 2020). "Since the tumor still showed high mTOR activity in the last resection, the everolimus treatment was once again started." (PMID 31309284, 2020). "Our findings demonstrated that INK128 successfully suppresses the mTOR signaling pathway and attenuates tumor growth and the degree of lung metastasis induced by low SLFN11 expression." (PMID 32292519, 2020). "Increased expression of PTEN and decreased AKT and mTOR were recorded when tumor cells of ovarian cancer xenograft-bearing nude mice were treated with 50-mg/kg EGCG." (PMID 33113766, 2020). "The downregulation of miRNA-30c will reduce mTOR activity and glycolysis in tumor-related macrophages." (PMID 32175074, 2020). "We also examined the primary tumor regarding mTOR activity retrospectively and found the same pattern of alterations." (PMID 31309284, 2020). "The functional enrichment analysis of the turquoise module that was correlated with the metastasis trait indicated that the genes in this module were enriched in tumor metastasis-associated KEGG pathways (PI3K-Akt, TGF-beta, mTOR, Jak-STAT, etc.)." (PMID 32899503, 2020). "This study demonstrated the role of mTOR inhibition on impaired tumour blood supply thus leading to inhibition of tumour growth." (PMID 32443649, 2020). "S100A10 activated the mTOR pathway by interacting with annexin A2 (ANXA2) to accelerate tumor glycolysis, resulting in tumor malignant progression." (PMID 33324631, 2020). "The enhanced effects observed in GBM tumour cells and GSCs support the necessity of dual PI3Kα and mTOR inhibition to efficiently disrupt GSCs 64,66." (PMID 33318517, 2020).
tumor (continued). "The important role of eEF-2K in mediating the resistance of tumor cells to mTOR inhibitors enlightens us that the development of effective inhibitors targeting eEF-2K has a good application prospect and can provide a new strategy for tumor treatment." (PMID 33144562, 2020). "An activated aberrant PI3K/protein kinase B (AKT)/mTOR signaling pathway results in a more aggressive tumor phenotype with enhanced angiogenesis, proliferation, metastases, and drug resistance." (PMID 32578154, 2020). "Due to an observed tumor re-growth associated with AKT/mTOR signaling activation, they further investigated the triple-targeting approach of cetuximab, bevacizumab, and the mTOR inhibitor temsirolimus in combination with irradiation." (PMID 32903756, 2020). "RNA-seq analysis revealed that RUNX1 was involved in various tumor-associated pathways, such as TNF, mTOR and focal adhesions, and that its downstream targets were involved in proliferation, apoptosis, invasion and epithelial-mesenchymal transition (EMT)." (PMID 32487998, 2020). "Molecular characterization of the glioneuronal tumor allowed to detect high levels of phosphorylated MTOR (pMTOR); therefore, a therapeutic approach based on an mTOR inhibitor (everolimus) was elected." (PMID 32806529, 2020). "In this study, we found that inhibition of miR-20b and overexpression of miR-451a had a tumor-suppressive role in GC through the regulation of genes involved in the PI3K/AKT/mTOR signaling pathway." (PMID 32013265, 2020). "Understanding mTOR inhibitor uptake in a model that resembles as close to real tumours is imperative towards the understanding of mTOR activity in the tumour environment." (PMID 33142217, 2020). "But in this light tendency to antagonism observed between GEM and MLN in MES-SA cell line still remains surprising, especially if we take into consideration known, important, role of mTOR pathway in metabolism of these tumours." (PMID 33173419, 2020). "Many literatures supported that autophagy was mediated by the AKT/mTOR pathway to inhibit tumor growth." (PMID 33015162, 2020). "The activation of the tumor-infiltrating immune cells was affected by the mTOR/AKT pathway as examined by the research in the field of immunology in the last decade." (PMID 31875150, 2019). "Initially, we checked the role of Lanatoside C in tumor-associated proteins such as AKT, PI3K, and mTOR." (PMID 31783627, 2019). "Of the known effectors of NF1-loss associated signaling, p38, STAT3, AKT, mTOR, and TGF-β have been previously linked to heightened tumor aggressiveness." (PMID 30967630, 2019). "Even PrPc degradation by the proteasome system was shown to decrease tumor progression, which is remarkable because the very same Akt/mTOR pathway synergistically modulates both p26S proteasome and ATG." (PMID 31618844, 2019). "mTOR regulates iNKT1 and iNKT17 differentiation via mTOR complex 1 (mTORC1) and mTORC2 and their tight regulation by the tumor suppressor TSC1 ensures proper iNKT1/17 balance." (PMID 31824499, 2019). "mTOR signaling mainly regulates cell proliferation and metabolism involved in tumor initiation and progression." (PMID 30754640, 2019). "This choice was driven by research in other tumor types that has shown that inhibition of mTOR only results in a feedback loop, activation of compensatory pathways, and tumor resistance." (PMID 31324855, 2019). "Several critical signaling pathways have been identified to have important roles in tumor angiogenesis, including the PI3k/Akt/mTOR, NF-휅B, Notch, Wnt/훽-catenin and Hedgehog signaling pathways." (PMID 31266540, 2019). "In view of the efficacy and safety associated with reductions in tumor volume and seizure frequency in TSC patients, mTOR inhibitor is a good choice of medical therapy." (PMID 30760308, 2019). "Simultaneously, upregulation of AMPK serves to halt the cell cycle and suppress tumor growth via inhibition of the mTOR signaling pathway." (PMID 31648230, 2019).